BRCA1 (BRCA1 DNA repair associated)
Diseases named in the same sentence as BRCA1 in open-access papers (continued):
Sharing a sentence is not in itself a finding about the gene and the disease.
breast cancer (continued). "The applicability of our results from murine breast tumor models to human BRCA1-related breast cancer is well supported by several levels of evidence." (PMID 27566577, 2016). "The terms triple-negative and basal-like breast cancer (BRCA1 genotype) have been used interchangeably, because breast cancer with a BRCA1 genotype represents a basal tumor subtype." (PMID 26981296, 2016). "Two proteins highly abundant in the BRCA1-deficient secretome, namely CDH3 and TOP1, were selected for validation in tumor tissue samples of breast cancer patients." (PMID 27566577, 2016). "Available literature is in agreement with regard to higher incidence of breast cancer than peritoneal cancer among BRCA1 carriers undergoing prophylactic salpingo-oophorectomy." (PMID 26928677, 2016). "Somatic mutation in cancer based on copy number, aberrations, nucleotide substitutions, and on subsets in breast cancer BRCA1/2 are found by dGene, DGIdb HER2, and ESR1 estrogen receptor (ER) gene mutations for finding a drug or kinase inhibitor." (PMID 26973813, 2016). "For example, it has been shown that BRCA1 transcription can be repressed by aberrant methylation in its promoter in sporadic breast cancer." (PMID 27788678, 2016). "Thus, we believe that α-lactalbumin vaccination may be both safe and effective in preventing TNBC in women with BRCA1 mutations who often have >80% lifetime risk for developing breast cancer with TNBC being the most common variant of this disease occurring in this high risk population." (PMID 27322324, 2016). "MiRNA-146a-5p has previously been reported to bind to BRCA1 3′UTR and its expression in breast cancer cells has been associated with increased proliferation and reduced homologous recombination." (PMID 26933805, 2016). "In this study, we investigated the methylation status of BRCA1 and 17βHSD-1 in sporadic breast cancer Egyptian patients and correlated the findings to those in normal breast tissues." (PMID 27413552, 2016). "MYC is a target of WNT/β-catenin signaling, which induces epigenetic repression of BRCA1 expression by means of snail family zinc finger 2 (SNAI2) and is associated with basal-like breast cancer and EMT, including metastasis." (PMID 27590516, 2016). "In one study with olaparib, women with BRCA1 or BRCA2 mutations and recurrent advanced breast cancer were assigned to two sequential cohorts in a phase 2 study." (PMID 27252813, 2016). "The complete coding regions of the BRCA1 and BRCA2 genes were screened for small-range mutations and large genomic rearrangements in all 523 breast cancer patients." (PMID 27553291, 2016). "An example of genetic susceptibility to breast cancer includes mutations in the breast cancer 1 (BRCA1) or BRCA2 gene, which results in a lifetime risk of breast cancer of between 60% and 85%." (PMID 27582548, 2016). "However, some trends could be observed, for example, all of the women with mutations in the BRCA2 gene with bilateral breast cancer were homozygous for the G allele in rs132281615, and among those with mutations in BRCA1 and with bilateral breast cancer, 86 % had at least one G allele." (PMID 26770289, 2016). "It should also be noted that we have studied only a small portion of possible mutations (5382insC, 4153delA, 185delAG and 300T> G in the BRCA1 gene, and 6174delT in the BRCA2 gene) in women with breast cancer in Uzbekistan." (PMID 29138730, 2016). "Women age 40 with stage I breast cancer and a first-degree relative with bilateral breast cancer have a QALY benefit from CPM similar to that reported for BRCA1/2 mutation carriers." (PMID 27650678, 2016). "Thus, while over 60% of women with a familial BRCA1 mutation will develop breast cancer before the age of 70, “metabolically healthy” lifestyles might be able to significantly reduce the likelihood of pre-tumoral BRCA1 haploinsufficient cells reaching the malignancy threshold." (PMID 26943589, 2016).
breast cancer (continued). "We performed a comprehensive testing of a panel of BRCA1-mutant and comparable BRCA1-wild-type breast cancer cell lines for sensitivity to 198 approved and investigational drugs to identify common vulnerabilities." (PMID 27313062, 2016). "We observed a strong decrease in BRCA1 with PI3K pathway blockade that was consistent with previous reports in breast cancer models." (PMID 27382432, 2016). "Consistent with its tumor suppressor role, forced expression of BRCA1 in breast cancer cells led to a marked reduction in endogenous IGF1R levels and promoter activity." (PMID 27446805, 2016). "HR defective cells, such as breast cancer cells harboring mutant BRCA1, display greater than normal sensitivity to poly ADP ribose polymerase 1 (PARP-1) inhibition." (PMID 27197561, 2016). "Mutations in the two major high-penetrance breast cancer genes, BRCA1 (breast cancer 1, early onset gene) and predominantly BRCA2 (breast cancer 2, early onset gene), account for approximately 10 % of MBCs outside populations with BRCA founder mutations." (PMID 26857456, 2016). "We examined an institutional cohort of breast cancer patients with germline BRCA1 (n=46) and BRCA2 (n=35) mutations and found that FOXC1 expression on immunohistochemical staining is associated with BRCA1 vs BRCA2 mutations [30/46 vs. 6/35]." (PMID 27708239, 2016). "It is well known that BRCA1, a key mediator of the DNA repair pathways, remain one of the most important genes for breast cancer." (PMID 26998311, 2016). "At the age of 70, cumulative cancer risk for BRCA1 and BRCA2 mutation carriers ranges from 43% to 88% for breast cancer development, and from 11% to 59% for ovarian cancer." (PMID 27015555, 2016). "Immunohistochemical analysis of IGF1R levels in breast tumor specimens derived from BRCA1/BRCA2 mutation carriers, compared to matched sporadic breast cancer patients, revealed higher IGF1R levels in tumors of BRCA mutation carriers." (PMID 27446805, 2016). "We tested growth-inhibiting effects of 198 FDA-approved and experimental drugs on four BRCA1-mutant and four comparable BRCA1-wild-type human breast cancer cell lines." (PMID 27313062, 2016). "These two breast cancer lines were chosen since they are known to express wild-type BRCA1 and luminal differentiation markers (some of which we targeted here)." (PMID 27487152, 2016). "First, we performed a quantitative investigation using FACT-B (Chinese version) and Irritability, Depression and Anxiety scale (IDA) to assess the QOL and PS in breast cancer patients who received BRCA1/2 genetic testing." (PMID 27428375, 2016). "In contrast, non-myocardial BxPC-3 and PANC-1 pancreatic cancer cells and MCF-7 and T47D human breast cancer cells exhibit pronounced nuclear BRCA1." (PMID 27494651, 2016). "While in a study with a larger sample size of 99 Chinese patients with hereditary breast cancer, 7.1% in BRCA1 and 11.1% in BRCA2 were found by NGS." (PMID 27257965, 2016). "We analyzed through array CGH the genomic profile of 47 biopsies, from hereditary breast cancer patients, 40 from BRCAX patients, 3 from BRCA1 and 4 from BRCA2 mutation carriers." (PMID 26979459, 2016). "Germline mutations in DNA mismatch repair genes (BRCA1, BRCA2, CHEK2, ERCC4, FAAP100, and TP53BP1, amongst others) are associated with breast cancer susceptibility." (PMID 27608040, 2016). "The mutation was found in 6 (0.7%) of 877 familial, mostly Caucasian, non-BRCA1/2 breast cancer cases, while the frequency in controls was 0.1% (OR = 5.7, 95% CI = 1.0–40.7, P = 0.02)." (PMID 27424772, 2016).
breast cancer (continued). "As haplotype analysis of BRCA1 c.5470_5477del8 mutation and BRCA2 c.3109C > T mutation had been performed in Chinese high risk breast cancer patients, we performed haplotype analysis on the other four recurrent mutations in this study." (PMID 26852015, 2016). "The characterization of BRCA1 and BRCA2 founder mutations and association between the founder mutations and breast cancer risk should be studied in a large-scale Chinese population size." (PMID 26852015, 2016). "Susceptibility to breast cancer can involve the tumor suppressors breast cancer-1 (BRCA1) and breast cancer-2 (BRCA2), which are also involved in ovarian cancer." (PMID 26840090, 2016). "To evaluate the association between NBS1 rs2735383 and breast cancer risk, we analyzed NBS1 rs2735383 by RFLP-PCR in 1,269 non-BRCA1/2 familial breast cancer patients and 1,159 controls from RBCS." (PMID 27845421, 2016). "The discovery of the germline mutations in BRCA1 and BRCA2 confirmed the presence of genetic predisposition for familial breast cancer." (PMID 27148484, 2016). "While both MCF10A and MCF10DCIS express wild-type BRCA1, HCC1937 is a model of BRCA1-deficiency breast cancer wherein one allele is mutated while the other is deleted." (PMID 27556296, 2016). "XIST's relationship with the breast cancer gene BRCA1 (which is a well-known tumour suppressor gene, TSG) has been widely studied." (PMID 30159409, 2016). "In the subgroup analysis, the highest overall BRCA1 and BRCA2 mutations rate was 50.0 % (8/16) in the breast cancer patients with family histories of ovarian cancer." (PMID 26852015, 2016). "Our previous studies showed that germline BRCA1 and BRCA2 mutations are associated with early onset breast cancer and familial breast cancer in Chinese women population." (PMID 26848770, 2016). "The function of TNRC9 is unclear, but a recent paper has reported that TNRC9 down-regulates BRCA1 expression and promotes breast cancer aggressiveness." (PMID 26911390, 2016). "Of the eight patients with a BRCA1/2 positive result, three had a personal history of breast cancer ≤ the age of 30 years." (PMID 26997744, 2016). "High sensitivity of BRCA1-driven tumors to cisplatin was initially demonstrated in a small Polish neoadjuvant breast cancer (BC) study involving mainly patients with small tumors." (PMID 27555886, 2016). "We demonstrate that pyrosequencing is an efficient and effective method to measure BRCA1 methylation level in breast cancer tissues." (PMID 27027444, 2016). "Breast cancer-related BRCA1 mutants display low ability to bind RHA thus reducing BRCA1 tumor suppressor activity and promoting cancer growth." (PMID 26885691, 2016). "BRCA1 methylation percentage in our study is near to the upper end of previously reported frequencies for this alteration in sporadic breast cancer." (PMID 27413552, 2016). "Among all features selected for analysis among BRCA1 carriers diagnosed with breast cancer before prophylactic surgery, only the survival feature was statistically significant (p = 0.00010)." (PMID 26928677, 2016). "One clear example is screening in the BRCA1/BRCA2 genes followed by adapted preventive measures (intensified mammography or removal surgery), which have been shown to significantly reduce breast cancer-associated risks among BRCA1/2 mutation carriers." (PMID 27776531, 2016). "We found a trend towards BRCA1 and 17βHSD-1 promoter hypermethylation in cancer tissue specimens of sporadic breast cancer patients compared with controls, although the difference was nonsignificant (p > 0.05)." (PMID 27413552, 2016).
breast cancer (continued). "BRCA1 promoter hyper methylation has been identified as an important mechanism for BRCA1 inactivation in sporadic breast cancer and appears to correlate with reduced BRCA1 mRNA and protein." (PMID 28164176, 2016). "We compared the VNTR genotype distributions in the XRCC5 promoter between three types of familial breast cancer: BRCA1+, BRCA2+, and BRCAx." (PMID 27148484, 2016). "Approximately 56% of these genes have been previously identified as up-regulated at 24 h post-estrogen stimulation, including known breast cancer genes BRCA1, BRCA2, and E2F1." (PMID 27539783, 2016). "It has been recently shown that concomitant BRCA1/2 downregulation following PI3K inhibition in breast cancer and prostate cancer is sufficient for the induction of HR deficiency, rendering cancer cells to acquire sensitivity to PARP inhibition." (PMID 26909613, 2016). "We previously summarized the spectrum of the germline mutations in these genes and found that the BRCA1 and BRCA2 tumor suppressor genes are the two most important susceptibility genes and account for nearly 98 % of hereditary breast cancer in China." (PMID 26852015, 2016). "Mutations in BRCA1 and BRCA2 genes explain approximately 15% of familial breast cancers and are the most common hereditary lesions in breast cancer." (PMID 27149669, 2016). "Silencing of BRCA1 gene via promoter hypermethylation is a common mechanism for its inactivation ranging from 9 to 44% of sporadic breast cancers." (PMID 27413552, 2016). "Together, these data support the idea that EZH2 negatively regulates FOXO3 transcription in BRCA1-deficient breast cancer cells, whereas this EZH2 activity is repressed by BRCA1 in BRCA1-competent cells." (PMID 27043660, 2016). "Our measurements showed that BRCA1 promoter methylation levels are significantly higher in breast cancer tissues than in matched normal tissues." (PMID 27027444, 2016). "The analysis of an extended set of breast cancer cell lines is recommended in order to better understand the relationship between miR-187-5p and BRCA1 expression." (PMID 26933805, 2016). "Germ-line or somatic inactivation of BRCA1 is a defining feature for a portion of human breast cancers." (PMID 27313062, 2016). "BRCA1 has been implicated as a negative regulator of AKT, targeting phosphorylated AKT for ubiquitination and degradation in mammary tumors." (PMID 27465688, 2016). "Less than 20 % of women affected by breast cancer (BC) and qualified for BRCA1/2 testing are carrying a deleterious (or pathological) mutation in one of these genes." (PMID 26758370, 2016). "Breast cancers arising in the setting of the hereditary breast cancer genes BRCA1 and BRCA2 are most commonly classified as basal-like breast cancer (BLBC) or luminal breast cancer, respectively." (PMID 27708239, 2016). "Our screen revealed a remarkable heterogeneity among the four BRCA1-mutant breast cancer cell lines in their responses to most drugs." (PMID 27313062, 2016). "We have shown that BRCA1 promoter methylation level in breast cancer is significantly higher than that in normal tissues." (PMID 27027444, 2016). "Large genomic rearrangements account for 4–28 % of all BRCA1 and BRCA2 mutations, and such mutations have been found in Chinese women at a high risk for breast cancer." (PMID 26852015, 2016). "Following PCR amplification and sequencing of BRCA1 and BRCA2, in 10 males with breast cancer, their variants and polymorphisms were detected." (PMID 27478808, 2016).
breast cancer (continued). "These were followed by reports from several other trials in BRCA1- and BRCA2-deficient breast cancer, ovarian cancer, melanoma, colorectal cancer, hepatocellular carcinoma, and cervical cancer." (PMID 28025559, 2016). "The treatment impeded the recruitment of 53BP1 and BRCA1 to the chromatin regions flanking DNA double-strand breaks and thereby avoided the DNA damage responses in breast cancer cells that were exposed to ionizing radiation." (PMID 27054335, 2016). "BRCA1 promoter methylation is correlated with poor overall outcomes for Caucasian and Chinese breast cancer patients." (PMID 27027444, 2016). "Earlier studies from our group have revealed the ability of PB (5-hydroxy-2-methyl-1, 4-naphthoquinone) to selectively target BRCA1-defective ovarian cancer cells as well as BRCA1-knockout breast cancer xenografts (unpublished data)." (PMID 27229859, 2016). "In this study we have investigated the role of BRCA1 in the regulation of transcription of large ribosomal RNAs and selected ribosomal proteins in breast cancer cells." (PMID 27589844, 2016). "Since the discovery of BRCA1 and BRCA2 as breast cancer susceptibility genes, much focus has been placed on discovering additional DNA variants that are associated with FBC development." (PMID 26969729, 2016). "Though association of CALD1 to breast cancer therapy outcome has been poorly assessed so far, ANXA1 expression was previously associated to BRCA1/2 mutation carriers and prediction of high mortality risk in Her2+ patients." (PMID 26657294, 2016). "Another PARP inhibitor, Olaparib (AZD-2281, AstraZeneca), showed response in 41% of women with BRCA1- and BRCA2-deficient breast cancer in a phase 2 trial." (PMID 28025559, 2016). "Promoter hypermethylation is the major transcriptional silencing mechanism in BRCA1, ranging from 13%–40% in sporadic breast cancer." (PMID 27027444, 2016). "Carriers of BRCA1 gene diagnosed with breast cancer should undergo prophylactic surgery within five years from the diagnosis of breast cancer." (PMID 26928677, 2016). "The results from the functional assays were incorporated into a joint analysis of 214 BRCA1 VUS to predict their likelihood of pathogenicity (breast cancer)." (PMID 28781887, 2016). "Women harboring a germline mutation in the BRCA1 gene show a lifetime cumulative risk (LCR) between 44 and 68 % of developing breast cancer until 70 years of age." (PMID 26770289, 2016). "The discovery of BRCA1 and BRCA2 made it for the first time possible to offer genetic testing to determine breast cancer risk." (PMID 27881737, 2016). "In breast cancer cells and mice models, BRCA1 limited ER and PR transcriptional activities and mitogenic actions." (PMID 27246982, 2016). "Both show strong similarities with BRCA1-mutant breast cancers and BRCA1 dysfunction, or ‘BRCAness’, is observed in a large proportion of sporadic BLBCs." (PMID 26943587, 2016). "Consistent with findings from human breast tumor cells, Neat1 knockdown suppressed in vitro self-renewal of CSCs in mouse Brca1 mutant mammary tumors." (PMID 27556296, 2016). "BRCA1-related cancers generally occur in younger women, before the age of menopause, and are more aggressive than breast cancers that arise in the general population." (PMID 27246982, 2016).